PTH (parathyroid hormone)
Diseases named in the same sentence as PTH in open-access papers (continued):
Sharing a sentence is not in itself a finding about the gene and the disease.
vitamin D deficiency (continued). "At the final stage, the vitamin D deficiency becomes very severe and 1,25(OH)2D synthesis is markedly inhibited, the calcitriol concentration decreases, and subsequently absorption of both calcium and phosphorus is impaired, along with persistent elevation of PTH and increased ALPL." (PMID 29904370, 2018). "Moreover, clinical trials with vitamin D supplementation in patients with vitamin D deficiency stratified according to PTH levels should be performed to test our hypothesis." (PMID 30662585, 2018). "Severe vitamin D deficiency or hypomagnesaemia might mimic PTH resistance." (PMID 29959430, 2018). "Vitamin D deficiency results in increased PTH levels, and PTH reduces the mechanical stress-induced NO production in human primary bone cells in vitro, suggesting that vitamin D might affect the response of osteocytes to mechanical loading via PTH." (PMID 29098573, 2017). "Patients with vitamin D deficiency (defined as 25(OH)D < 10 ng/mL), insufficiency (defined as 25(OH)D < 20 ng/mL), or hyperparathyroidism (PTH > 65 pg/mL) were supplemented with cholecalciferol 16.000IU (0.266 mg) weekly (if deficiency) or fortnightly (if insufficiency or high PTH levels)." (PMID 27699068, 2016). "Therefore, people with vitamin D deficiency might have normal blood calcium levels and a high PTH level as a result of secondary hyperparathyroidism." (PMID 26942211, 2016). "The mechanisms responsible for osteopenia and osteoporosis are uncertain and multifactorial, but exposure to certain antiretroviral drugs (in particular a NRTI: tenofovir-TDF-and the PI class), aging, HIV itself, parathormone (PTH) increase, and vitamin D deficiency may be implicated." (PMID 26273302, 2015). "Increased levels of parathyroid hormone (PTH) cause an increase in bone turnover that is associated with bone loss, predominantly cortical; secondary hyperparathyroidism has been proposed as the main mechanism through which vitamin D deficiency contributes to the pathogenesis of hip fracture." (PMID 25705670, 2015). "In addition, we also tested whether plasma levels of parathyroid hormone (PTH), which increases in vitamin D deficiency, are associated with sun exposure, season of blood draw and 25(OH)D." (PMID 22518130, 2012). "The mechanisms responsible for osteopenia and osteoporosis are uncertain but exposure to certain antiretroviral drugs (in particular a NRTI: tenofovir--TDF--and the PI class), aging, HIV by itself, parathormone (PTH) increase, and vitamin D deficiency may be implicated." (PMID 22333484, 2012). "However, it is not known whether these agents are effective and safe in reducing PTH levels in postmenopausal women with pHPT and concomitant vitamin D deficiency, particularly in the longer term." (PMID 23781299, 2012). "The typical biochemical signature of vitamin D deficiency includes low serum 25OHD levels, elevated alkaline phosphatase (ALP), elevated parathyroid hormone (PTH) and normal/low serum calcium and phosphate." (PMID 40075827, 2025). "In contrast, those with severe vitamin D deficiency exhibit an increased CAD risk, possibly due to elevated parathyroid hormone (PTH) levels, which is a highly sensitive indicator of vitamin D deficiency and has established cardiovascular implications." (PMID 40610878, 2025). "For the DT model, the 5 most predictive features were CKD, hyperparathyroidism (PTH>6.8pmol/L), advanced age (>80 years), presence of CAD and vitamin D deficiency (≤25nmol/L)." (PMID 39746010, 2025). "Endocrine evaluation demonstrated elevated parathyroid hormone (PTH) with vitamin D insufficiency, elevated alkaline phosphatase, and normal phosphate, a pattern consistent with secondary hyperparathyroidism." (PMID 41322841, 2025). "The elevated PTH levels among RYGB patients are presumably caused by malabsorption and/or vitamin D deficiency, i.e., secondary hyperparathyroidism." (PMID 39865206, 2025).
vitamin D deficiency (continued). "Vitamin D deficiency is a well-recognized confounder in the management of PHPT and can contribute to persistently elevated PTH levels even after resection of a hyperfunctioning gland." (PMID 41393630, 2025). "One-third of participants had vitamin D insufficiency, while a quarter showed high PTH levels despite normal calcium." (PMID 41149617, 2025). "For the XGB model, the 5 most predictive patient features were advanced age (>80 years), vitamin D deficiency (≤25nmol/L), CKD, CAD and hyperparathyroidism (PTH>6.8pmol/L)." (PMID 39746010, 2025). "Vitamin D insufficiency (25OHD 50–74.9 nmol/L) was common at baseline, and weekly oral administration of 10 000 IU vitamin D3 for 3 yr was effective in suppressing serum PTH concentrations and elevating 25OHD concentrations above the 75 nmol/L threshold." (PMID 38477739, 2024). "The present study aimed to evaluate the effects of aquatic training and vitamin D3 supplementation on femur bone mineral density (BMD), serum 25(OH)D, and parathyroid hormone (PTH) in postmenopausal obese women with vitamin D insufficiency." (PMID 38299108, 2024). "In the total sample, 25-OHD and PTH were negatively correlated, and all subjects with high PTH presented vitamin D insufficiency (25-OHD < 75 nmol/L)." (PMID 39408619, 2024). "Subsequently, PTH and 25-hydroxy vitamin D levels were requested, which revealed suppressed PTH level (0.8 pmol/L) alongside vitamin D insufficiency (39 nmol/L)." (PMID 39434928, 2024). "Vitamin D insufficiency or deficiency is commonly noted in asymptomatic PHPT and is associated with higher PTH levels and higher markers of bone turnover such as bone-specific alkaline phosphatase." (PMID 38115826, 2023). "It is estimated that the prevalence of vitamin D deficiency and insufficiency in PHPT has decreased by 50% and 30%, respectively, with a corresponding decline in PTH levels." (PMID 38115826, 2023). "Our findings reveal that serum PTH levels significantly increased in the vitamin D insufficiency group compared to the sufficiency group." (PMID 36834562, 2023). "Some experts suggest repletion to 25(OH)D levels above 30 ng/mL (75 nmol/L), as there is evidence that even vitamin D insufficiency increases PTH levels." (PMID 38115826, 2023). "After 12 weeks of nordic-walking training, a decrease in PTH concentration was observed among postmenopausal women with baseline vitamin D insufficiency (below 18.6 ng/ml), which corresponds to the results obtained in our study." (PMID 35514345, 2022). "Several of the patients with low vitamin D had other biochemical features of vitamin D deficiency, such as low serum calcium and high ALP and PTH." (PMID 35426179, 2022). "Generally, vitamin D deficiency is described as a serum 25-OHD concentration of <20 ng/mL (50 nmol/L), which is a cut-off point from where parathyroid hormone starts to rise, which is the physiological definition of vitamin D deficiency." (PMID 36012852, 2022). "PTH and ALP were normal in most of the patients with mild vitamin D deficiency and those with vitamin D insufficiency, which possibly explains the lack of symptoms in those patients whose vitamin D levels were above 15 ng/mL." (PMID 36428888, 2022). "Subjects with vitamin D deficiency (< 20 ng/ml) have increased us-CRP and PTH compared with those with insufficiency (20-32 ng/ml) or optimal concentrations (> 32 ng/ml)." (PMID 34991572, 2022). "In the vitamin D insufficiency group (20 to <30 ng/mL), PTH was high in 25.5%, and ALP was high in 8%." (PMID 36428888, 2022). "Parathyroid hormone (PTH) was elevated at 172.5 pg/mL and increased to 443 pg/mL after correction of vitamin D deficiency." (PMID 36457632, 2022). "The proportion of vitamin D deficiency (VDD) reached 81.8% (9/11), and PTH slightly increased in two patients due to VDD." (PMID 36339419, 2022).
vitamin D deficiency (continued). "A vitamin D deficiency is common in CKD patients, and low circulating 25(OH)D levels are invariably associated with high serum parathyroid hormone (PTH) levels as well as with bone mineralization defects, such as osteomalacia in case of severe forms." (PMID 35323709, 2022). "Age, gender, albumin level, PTH level, and SOFA score were significantly associated with vitamin D deficiency in these patients." (PMID 34966771, 2021). "The longer-term effects of persistent vitamin D insufficiency/deficiency in survivors of critical illness also require further investigation especially in the context of bone health, which could be independently evaluated using sequential measurement of bone turnover markers and serum PTH." (PMID 34686560, 2021). "The median time between the relevant event (vitamin D insufficiency or elevated PTH) and transplant was 83 days (IQR: 40–146 days)." (PMID 34356591, 2021). "In the multivariable analysis, young age, female gender, low albumin level, high PTH level, and high SOFA scores were significantly associated risk factors for vitamin D deficiency." (PMID 34966771, 2021). "More than one-third of the patients were diagnosed with Vitamin D insufficiency or deficiency, but serum Ca, P, ALP, and PTH were at approximately normal levels." (PMID 34429096, 2021). "By multivariate logistic regression analysis, vitamin D insufficiency was an independent predictor of postoperative PTH reduction ratio ≥ 50% (OR = 2.2, p=0.017)." (PMID 34956363, 2021). "Additional laboratory testing on the participant showed low 25-OH-Vitamin D level (10.33 ng/mL), suggesting an incidental abnormal PTH finding due to vitamin D insufficiency." (PMID 33921839, 2021). "According to the multivariable analysis, young age, female gender, low albumin level, high parathyroid hormone (PTH) level, and high sequential organ failure assessment (SOFA) score were significantly associated risk factors for vitamin D deficiency." (PMID 34966771, 2021). "Furthermore, it should be mentioned that elevated PTH may contribute to the pathogenesis of sarcopenia, given its direct effect on skeletal muscle protein metabolism and the recent demonstration that elevated PTH levels are associated with vitamin D deficiency in sarcopenia." (PMID 33923948, 2021). "Young age, female gender, low albumin level, high PTH level, and high SOFA score are significantly associated risk factors for vitamin D deficiency." (PMID 34966771, 2021). "This makes PTH level another marker for vitamin D insufficiency, but its values tend to normalize after proper cholecalciferol supplementation." (PMID 34065169, 2021). "The predictive value of our models significantly increased in subjects with CKD with up to 30% of PTH variation explained by GFR in those with stage 3a to 4 CKD and vitamin D deficiency." (PMID 33995282, 2021). "The low rate of concurrent PTH and ALP measurement caused difficulties in interpreting the severity of vitamin D deficiency." (PMID 31893581, 2020). "People with increased parathyroid hormone level in response to vitamin D insufficiency tend to have extracapsular fractures, while persons with muted parathyroid hormone response presented more commonly due to intracapsular fractures." (PMID 32280678, 2020). "An alternative strategy of measuring calcium and parathyroid hormone (PTH) to detect secondary hyperparathyroidism, inferring vitamin D deficiency, has been suggested as a functionally more meaningful marker of vitamin D deficiency." (PMID 32290515, 2020). "Serum calcium, PTH, and 1,25(OH)D concentrations were significantly higher in subjects with PHP when compared with values in heathy volunteers and subjects with vitamin D deficiency." (PMID 33210066, 2020). "Mean serum levels of parathyroid hormone (PTH), calcium, and phosphorus in relation to vitamin D deficiency and insufficiency." (PMID 32821633, 2020).
vitamin D deficiency (continued). "Continuous ambulatory peritoneal dialysis (CAPD) patients have a high incidence of stroke and commonly have increased parathyroid hormone levels and vitamin D insufficiency." (PMID 32423377, 2020). "Ca and PTH levels were elevated at 3.23 mmol/l (12.9 mg/dl) and 37.6 pmol/l respectively while there was evidence of vitamin D insufficiency (44 nmol/l)." (PMID 31797261, 2020). "Although we observed an inverse relationship between vitamin D and PTH in individuals with severe 25(OH)D deficiency, most of the individuals having vitamin D in the mid-range and those that have vitamin D insufficiency have normal PTH levels." (PMID 32821633, 2020). "In this context, when the patients are affected only by vitamin D insufficiency, the initial elevation of PTH levels is clearly different from the defined picture of SHPT that is observed mainly when 25(OH)D levels are markedly lower than 20 ng/mL." (PMID 31064117, 2019). "An inverse relationship between 25(OH)D levels and PTH concentration has been reported for preadolescents and adolescents and it has been suggested that the level of 25(OH)D at which PTH is suppressed could provide insight in to what the 25(OH)D threshold for vitamin D deficiency may be." (PMID 31159206, 2019). "Its deficiency (vitamin D deficiency—VDD), being common in European population, combined with elevated concentration of parathyroid hormone (PTH), represents a vicious cycle of mechanisms leading to heart failure (HF)." (PMID 29599854, 2018). "Nutritional rickets due to vitamin D deficiency was confirmed with knee radiographs, elevated serum ALP and PTH, and low 25OHD of < 5.2 nmol/L." (PMID 29940979, 2018). "According to our vision, the CVR would increase only among those patients in which the vitamin D insufficiency leads to increased serum PTH." (PMID 30662585, 2018). "SHPT is manifested by a defined triad including elevation of parathyroid hormone (PTH), vitamin D deficiency, and impairment of mineral metabolism." (PMID 28975108, 2017). "Vitamin D deficiency and elevated levels of ALP, ferritin, and PTH were identified as predictors of metabolic syndrome or poor prognosis of CVD in previous studies." (PMID 28327105, 2017). "Different from normal FGF23 and PTH, serum 25-hydroxyvitamin D was significantly lower in AnkKI/KI mice and vitamin D insufficiency was found in four out of seven CMD patients." (PMID 27784318, 2016). "Vitamin D deficiency is highly prevalent in patients with chronic kidney disease (CKD), and nutritional vitamin D supplementation decreases elevated parathyroid hormone concentrations in subgroups of these patients." (PMID 25883412, 2015). "Combination of vitamin D deficiency and TDF increased PTH compared to groups C and TDF, but this elevation was moderate compared to VDD." (PMID 25048368, 2014). "The level associated with optimal suppression of circulating PTH levels has been used to define criteria for vitamin D insufficiency, because of the inverse relationship between serum 25(OH)D and PTH." (PMID 25394580, 2014). "The subjects were divided into three groups: ten with vitamin D insufficiency (low vitamin D and raised PTH); ten with functional hypoparathyroidism (low vitamin D and low/low normal PTH); and ten who were vitamin D replete (normal vitamin D and normal PTH)." (PMID 23981518, 2013). "Targeting PTH synthesis by treating the active vitamin D insufficiency is the generally accepted standard of care." (PMID 23509710, 2013). "Vitamin D insufficiency is associated with high levels of BTMs (including OC, β-CTX, P1NP, and PTH) in young individuals, so we also examined the 25(OH)D levels in our 35- to 45-year-old subjects to avoid its effect on BTMs." (PMID 23533403, 2013). "Vitamin D insufficiency and secondary hyperparathyroidism lead to PTH related phospholipase C activation in adiposities, a process, which is followed by increase in intracellular calcium." (PMID 22998754, 2012).
vitamin D deficiency (continued). "In teens and adults, parathyroid hormone (PTH) and bone specific alkaline phosphatase (BALP) are elevated in vitamin D deficiency and are associated with enhanced bone turnover." (PMID 22413062, 2012). "In conjunction with parathyroid hormone (PTH), vitamin D plays a critical role in calcium homeostasis, and as a result, vitamin D deficiency has been implicated in osteoporotic and stress-related fractures." (PMID 19807897, 2010). "Aging, vitamin D deficiency, and hereditary reduction of CaSR expression/activity are causally linked to hyperparathyroidism, but how these conditions alter PTH secretory dynamics has not been fully characterized." (PMID 40492090, 2025). "This can manifest as primary hyperparathyroidism caused by overactive parathyroid glands excessively producing parathyroid hormone (PTH), or secondary hyperparathyroidism where an exogenous factor such as CKD or vitamin D deficiency stimulates increased PTH production." (PMID 40529990, 2025). "While we excluded patients with secondary hyperparathyroidism due to vitamin D deficiency and renal insufficiency, those on anti-resorptive therapy prior to PTH measurements were not excluded." (PMID 40608198, 2025). "In this study, we observed that supplementation of vitamin D3 and calcium not only could reduce serum levels of PTH and β-CTX, but also could slightly increase BMD of young patients with DTC and vitamin D insufficiency or deficiency." (PMID 40048011, 2025). "Three of them reported a significant negative correlation between serum PTH and vitamin D levels, supporting the presence of secondary hyperparathyroidism in the context of vitamin D deficiency." (PMID 40867540, 2025). "Studies in both humans and animal models found that even when PTH was not elevated, or when PTH levels varied widely, aminoaciduria persisted as long as vitamin D deficiency was present." (PMID 41142409, 2025). "This eucalcemic PTH elevation correlates with preoperative levels > 225 pg/mL and vitamin D deficiency, suggesting ongoing skeletal recovery processes rather than surgical failure." (PMID 41227247, 2025). "By examining correlations with biochemical markers such as parathyroid hormone (PTH), alkaline phosphatase, and serum phosphate, the researchers recommended lower, population-specific thresholds—designating vitamin D insufficiency at levels under 13.5 ng/mL and deficiency at levels below 7 ng/mL." (PMID 41586232, 2025). "Six patients showed elevated PTH despite normal calcium at 12 months, and all were found to have vitamin D deficiency, indicating that the abnormal PTH values were likely related to secondary factors rather than recurrent disease." (PMID 41323977, 2025). "The finding that PTH was the strongest negative predictor of 25(OH)D in both groups aligns with its physiological role as a compensatory hormone in vitamin D deficiency." (PMID 40431396, 2025). "Laboratory tests showed a high parathyroid hormone (PTH) level of 423 pg/ml, 25(OH)vitamin D deficiency at 14.26 ng/ml, and calcium levels were not determined." (PMID 39886673, 2024). "With values of 24,25(OH)2D3 and VMR in the opposite range of the axis (including severe vitamin D deficiency), such a relationship was absent and PTH values above the median predominated at all ages." (PMID 39281298, 2024). "In a previous study, the effect of vitamin D3 supplementation and the influence of Bsm1 in elderly women with vitamin D insufficiency was that the treatment increased the vitamin levels and reduced PTH, CRP, and 1-acid glycoprotein in patients with BB and Bb genotypes but not those with bb." (PMID 39335504, 2024). "In addition, our findings suggest that PTH proteoforms have significant potential as biomarkers for monitoring calcium homeostasis, particularly in patients with T2DM who also experience vitamin D deficiency." (PMID 39449502, 2024). "We found serum PTH fragments associated with vitamin D deficiency in patients with and without T2DM." (PMID 39449502, 2024).